IL7 (interleukin 7)
Diseases named in the same sentence as IL7 in open-access papers (continued):
Sharing a sentence is not in itself a finding about the gene and the disease.
Glucose intolerance (2 papers, 2010 to 2012). Glucose intolerance (GI) can be defined as dysglycemia that comprises both prediabetes and diabetes. "In lymphocyte-deficient SCID mice, this IL-7-mediated effect on B-cells is lacking, leading to uncontrolled macrophage infiltration and loss of IL-7 protective effect against glucose intolerance." (PMID 22768283, 2012). "Importantly, IL-7 protection against nutrient excess-induced glucose intolerance is lost in lymphocyte-deficient animals, suggesting that this protective effect of IL-7 evolves from a lymphocyte-dependent step of the inflammatory process that develops in the obese tissue." (PMID 22768283, 2012). "In IL-7-treated HFD-fed wild-type animals, the reduced WAT mass is expectedly associated to protection against glucose intolerance that results from a decreased inflammation in WAT." (PMID 22768283, 2012). "Secondly, in condition of nutrient excess such as high-fat diet feeding, IL-7 protects durably against inflammation, and thus glucose intolerance, possibly by regulating the recruitment of immune cells - the canonical IL-7 responsive cell-types - to the inflamed adipose tissue." (PMID 22768283, 2012). "In contrast, IL-7 injection did not protect anymore against HFD-induced glucose intolerance in lymphocyte-deficient SCID mice." (PMID 22768283, 2012). "Indeed, in vivo glucose clearance was severely delayed in Tg IL-7 animals compared with WT mice, indicating glucose intolerance." (PMID 22768283, 2012). "Therefore, one could propose that IL-7, by decreasing the recruitment of these pathogenic B-cells in the adipose tissue, will limit macrophage recruitment/activation and thus, inflammation, consequently leading to the observed protective effect against glucose intolerance." (PMID 22768283, 2012). "Interestingly, despite the beneficial effects of IL-7 on the MSG treatment, IL-7 alone was responsible for a slowly developing (from 60 minutes after glucose administration) state of a mild, yet significant, glucose intolerance (P-7 vs P-P, p<0.05)." (PMID 20376352, 2010). "This leads to conclude that, whereas the effects of IL-7 on WAT mass are lymphocyte-independent, its protective role against HFD-induced glucose intolerance requires the presence of functional lymphocytes." (PMID 22768283, 2012). "We confirm that high-fat diet is associated with increased expression of macrophage specific markers in the adipose tissue and show that a single and early injection of IL-7 is sufficient to durably impede this HFD-induced effect, consequently protecting mice against glucose intolerance." (PMID 22768283, 2012). "However, IL-7-triggered resistance against WAT inflammation and glucose intolerance is lost in SCID mice." (PMID 22768283, 2012).
graft versus host disease (2 papers, 2012 to 2016). An immune system disorder that occurs after allogeneic hematopoietic stem cell transplant and is a reaction of donor immune cells against host tissues. "Besides studies on thymus function in humans, TRECs have also been used in studies on aging mice, as well as studies on peripheral effects of IL-7 on RTEs in mice and in experimental graft-vs-host disease (GVHD)." (PMID 22590596, 2012).
head and neck squamous cell carcinoma (2 papers, 2014 to 2021). A squamous cell carcinoma that arises from any of the following anatomic sites: lip and oral cavity, nasal cavity, paranasal sinuses, pharynx, larynx, and salivary glands. "IL-7 gene is expressed in many solid tumors including head and neck squamous cell carcinoma, renal, esophageal, and Warthin's tumour of the parotid gland." (PMID 24653834, 2014).
Headache (2 papers, 2018 to 2023). Cephalgia, or pain sensed in various parts of the head, not confined to the area of distribution of any nerve. "Furthermore, headache was reported by 5 of the 18 healthy volunteers in a study that investigated the safety of GSK2618960, an IL‐7 receptor‐α subunit (CD127) monoclonal antibody, suggesting that dysregulation in the IL-7 levels could be associated with headache." (PMID 38022684, 2023). "Headache was predicted mainly by IL-5 and to a lesser extent by MIP-1β, while arthralgia was predicted by IL-1ra and IL-7." (PMID 29774022, 2018).
heart failure (2 papers, 2022 to 2025). Inability of the heart to pump blood at an adequate rate to meet tissue metabolic requirements. "Taken together, the high expression and activation of IL7Rα, PI3K/Akt, and Jak2/STAT5, we infer that the IL7 signaling pathway is activated in macrophages within the granuloma of patients with heart failure." (PMID 40521183, 2025). "The levels of TNF-α and IL-7 were significantly higher in the saliva of patients with heart failure and normal saliva secretion compared to the controls, as was the content of IL-1β, TNF-α and IL-7 in the saliva of patients in the study group with hyposalivation compared to the control group." (PMID 36300113, 2022).
invasive breast carcinoma (2 papers, 2010 to 2022). A carcinoma that infiltrates the breast parenchyma. "While not much is known about its role in solid tumors, recently it was shown that aberrant expression of IL-7 and its signaling intermediates in invasive breast cancers could have significant diagnostic and prognostic implications." (PMID 20964848, 2010). "The aim of this study has been to explore whether there is any elevation of interleukin-7 serum levels in early invasive breast cancer (EIBC) patients in comparison with healthy controls." (PMID 35794603, 2022). "We examined the contribution of IL-7 to early invasive breast cancer." (PMID 35794603, 2022).
ischemic stroke (2 papers, 2023). A stroke disorder caused by obstruction of blood flow to the brain, due to thrombotic (local blood clot formation) or embolic (due to a blood clot or other material traveling from another site) event. "Li's study showed that the serum IL-4, IL-5, IL-7, and IL-9 levels decreased in the ischemic stroke patients with poor outcome." (PMID 36875689, 2023).
liver cancer (2 papers, 2023 to 2025). An epithelial or non-epithelial malignant neoplasm that arises from the liver. "The expression of IL-7 by CAR T-cells enhanced activity in a liver cancer model, and the co-expression of IL-12 by modified TCR T-cells may be associated with improved anti-tumor immune response." (PMID 40282478, 2025). "Interestingly, a significant tendency for co-occurrence between IL7 and MAL2 was only found amongst the top ten upregulated genes in the TCGA liver cancer database (p < 0.001)." (PMID 37958451, 2023).
Lymphadenopathy (2 papers, 2011 to 2023). Enlargement (swelling) of a lymph node. "The ensuing lymphadenopathy is associated with increased production of IL-7 due to expansion of fibroblastic reticular cells, the primary source of this cytokine." (PMID 22102903, 2011). "The origin of this homeostasis disturbance could be attributed to self and commensal antigen-induced lymphadenopathy, resulting in expansion of IL-7-producing FRCs and down-regulation of IL-7R in chronically activated T cells." (PMID 22102903, 2011). "Because lymphadenopathy may also lead to the expansion of cells that produce IL-7, we examined IL-7 expression as well as frequency of fibroblastic reticular cells (FRCs), the major producers of this cytokine in secondary lymphoid organs." (PMID 22102903, 2011). "IL-7 stimulation also enhanced HIV-1-specific CD8+ T cell cytotoxicity, and lymphadenopathy occurred following subcutaneous (SC) IL-7 injection due to cell migration." (PMID 37767312, 2023).
malnutrition (2 papers, 2020 to 2023). Inadequate nutrition resulting from poor diet, malabsorption, or abnormal nutrient distribution. "Vitamin D modulates pro-inflammatory cytokines that are associated with malnutrition, i.e., IL-1, Il-7, TNF-α." (PMID 36983369, 2023). "To examine the impact of malnutrition on other pro-inflammatory cytokines in T2DM, we measured the circulating levels of pro-inflammatory cytokines (G-CSF, GM-CSF, MCP-1, MIP-1β, IL-6, IL-7, IL-8, IL-12p70 and IL-1β) in LBMI and NBMI individuals." (PMID 33183277, 2020).
myocardial ischemia (2 papers, 2023 to 2024). A disorder of cardiac function caused by insufficient blood flow to the muscle tissue of the heart. "Interleukin-7 (IL‐7), mainly produced by thymic stromal cells, aggravated myocardial ischemia/reperfusion (I/R) injury by promoting CM apoptosis through the regulation of macrophage M1 polarization and chemotaxis." (PMID 37587464, 2023).
Neonatal sepsis (2 papers, 2014 to 2020). Systemic inflammatory response to infection in newborn babies. "Nevertheless, further studies are necessary to understand the real role of IL-7 in the pathogenesis of neonatal sepsis." (PMID 25614712, 2014). "The potential of using IL-7 as a lymphostimulating therapy for septic patients has been described in previous studies and could also be explored in the context of neonatal sepsis." (PMID 32479514, 2020).
nephrotic syndrome (2 papers, 2023 to 2025). A collection of symptoms that include severe edema, proteinuria, and hypoalbuminemia; it is indicative of renal dysfunction. "IL-9, also released by T cells, seems to act antagonistically to IL-7 on the podocyte in nephrotic syndrome pathogenesis." (PMID 39946431, 2025). "More recently, podocytes simulation by IL-7 was shown to impair the glomerular filtration barrier, thus leading to nephrotic syndrome in adriamycin-treated rats." (PMID 36672735, 2023).
Opportunistic infection (2 papers, 2012 to 2013). An infection that is caused by a pathogen that would generally not be able to cause an infection in a host with a normal immune system. "The development of IL-7 therapy for the prevention of opportunistic infections and relapses or incidence of new malignancies is ongoing in the setting of post-HSCT and HIV infection." (PMID 22383042, 2012).
oral cancer (2 papers, 2025). "A three-gene expression signature including IL-7, LTB, and CXCL13 was associated with LN neogenesis in human oral cancer, where higher grades of TLS were associated with improved disease-free survival (DFS) and overall survival (OS)." (PMID 40475770, 2025).
osteonecrosis (2 papers, 2024). A none disease characterized by death of bone tissue due to a lack of blood supply. "With the exception of bFGF, IL-2RA, and IL-2, other cytokines such as VEGF, GRO-α, Trail, MIG, IL-7, and IL-17 did not demonstrate any association with osteonecrosis risk in the IVW primary MR analysis or secondary analyses." (PMID 38745949, 2024). "Except for IL-4, none of the other cytokines (e.g., VEGF, GRO-α, Trail, MIG, IL-7, IL-17) were shown to be associated with the risk of osteonecrosis in the IVW primary MR analysis or other secondary analyses." (PMID 38357652, 2024). "Except for IL-4 and IL-1RA, none of the other cytokines (e.g., VEGF, GRO-α, Trail, MIG, IL-7, IL-17) were shown to be associated with the risk of osteonecrosis in the IVW primary MR analysis or other secondary analyses." (PMID 38357652, 2024). "Except for SCGF-b, none of the other cytokines (e.g., VEGF, GRO-α, Trail, MIG, IL-7, IL-17) were shown to be associated with the risk of osteonecrosis in the IVW primary MR analysis or other secondary analyses." (PMID 38357652, 2024).
Parasitemia (2 papers, 2016 to 2018). "Parasitemia was significantly correlated with the following cytokines, in order of strength of association: IL-10, IL-12, TNF-α, IFN-γ, IL-1β, IL-6, IL-5, IL-2, IL-4, and IL-7." (PMID 27418744, 2016). "These cattle are known to be tolerant to different endemic parasitic diseases, and so the immunity-related genes within the candidate regions identified (e.g. LTA4H, IL7, IL15, FCN, LTA4H and NFAM1) are potential targets of natural selection." (PMID 30114214, 2018).
Pleural effusion (2 papers, 2022 to 2025). The presence of an excessive amount of fluid in the pleural cavity. "Importantly, we show that MPM patients with high IL‐7 level in pleural effusion have poorer survival." (PMID 36054746, 2022). "In pleural effusions (PEs), we found that IL‐7 concentration was not a good diagnostic biomarker." (PMID 36054746, 2022). "ROC curve data for ability of IL‐7 and SMRP to differentiate MPM from ADCA and/or BPE in pleural effusions." (PMID 36054746, 2022). "The results showed that CXCL16 was significantly higher in the MPE of LCP than in the pleural effusion of HP, whereas BAG6 and IL-7 did not exhibit statistically significant difference." (PMID 40959273, 2025).
polyp (2 papers, 2021 to 2022). A usually exophytic mass attached to the underlying tissue by a broad base or a thin stalk. "Nasal polyp samples demonstrated few to moderate IL-7 positive epitheliocytes, and numerous positive cells in connective tissue were found." (PMID 34208325, 2021).
preeclampsia (2 papers, 2023). Preeclampsia is a hypertensive disorder of pregnancy that is characterized by new-onset hypertension with proteinuria presenting after 20 weeks of gestation, and depending on mild or severe forms may initially present with severe headache, visual disturbances, and hyperreflexia. "As a state of chronic inflammation, overweight will increase the risk of preeclampsia by means of activating macrophages, NK cells, and peripheral helper T cells within the placenta to produce inflammatory cytokines such as IL-6, IL-7, and TNF-α." (PMID 36833689, 2023).
prostatic diseases (2 papers, 2011 to 2015). "In order to verify, at the systemic level our findings from BPH and localized PCA tissues, we comparatively evaluated circulating titres of IL-6, IL-7 and IL-15 in pre-operative sera from patients with prostatic diseases." (PMID 21943235, 2011). "Given the development of spontaneous prostatitis in NOD mice, that have defective T-reg responses, and the demonstrated role of IL7 in switching from FoxP3+ve T-regs to IL17 producing cells, this hypothesis is under active investigation." (PMID 25933188, 2015).
pulmonary arterial hypertension (2 papers, 2021 to 2024). Pulmonary arterial hypertension (PAH) is a group of diseases characterized by mean pulmonary artery pressure >20 mmHg and elevated pulmonary arterial resistance leading to right heart failure. "Numerous cytokines elevated in our study, such as IL-1α, IL-4, IL-5,IL-6, IL-7, IL-8, TNF-α were previously shown to involved in VOC-related acute clinical complications such as acute chest syndrome, pulmonary hypertension, and pulmonary thrombosis." (PMID 38361924, 2024).
renal fibrosis (2 papers, 2022 to 2023). A final common manifestation of a wide variety of chronic kidney diseases characterized by glomerulosclerosis and tubulointerstitial fibrosis. "Pro-fibrotic cytokines, including IL-7, IL-13, and IL-8, promote the expression of Thy-1 genes and sThy-1 release from renal interstitial fibroblasts, leading to renal fibrosis and ultimately the development of CKD." (PMID 37711613, 2023). "Whether a decline in IL7 may also promote renal fibrosis in canines is not clear." (PMID 35723372, 2022).
silicosis (2 papers, 2023 to 2024). Silicosis is a respiratory disease caused by breathing in (inhaling) silica dust. "After identifying pathogenic CD69+CD103- subsets, we highlight IL-7 for their maintenance and function, that present a promising avenue for mitigating silicosis." (PMID 39122899, 2024). "Whereas neutralizing IL-7 in the lung disrupted the maintenance of TRM-Teff cells during silicosis progression and exerted protective effects." (PMID 39122899, 2024). "Patients with silicosis seem to have a chronic inflammatory process that is consistent with the augmented levels of some pro-inflammatory cytokines, i.e., IL-1β, IL-6, IL-7, IL-8, IL-16, IL-17A, IL-33 and TNF-α were observed in this work." (PMID 36675056, 2023). "Neutralizing IL-7 alleviated silicosis by disrupting TRM-Teff maintenance." (PMID 39122899, 2024). "Besides, bronchoalveolar lavage appending IL-7 neutralizing treatment may provide postponing effects to silicosis in the advanced stage." (PMID 39122899, 2024).
skin cancer (2 papers, 2014 to 2025). "In summary, our findings underscore the potential of IL-7, IL-1RA, and CXCL-13 not only as mechanistically informative cytokines but also as a combined biomarker score for risk stratification for the occurrence of irAEs in skin cancer patients." (PMID 41394871, 2025).
skin inflammation (2 papers, 2014 to 2022). "Blockade of IL-7 signaling itself has been shown to acutely diminish γδ17-driven dermatitis while during viral hepatitis IL-7 co-operates with IL-23 to rapidly activate intrahepatic γδ17 cells and initiate inflammation." (PMID 25566265, 2014). "We have recently demonstrated that in γδ17 cells, STAT5-mediated IL-7 signaling induces surface expression of the checkpoint receptor B and T lymphocyte attenuator (BTLA), which is necessary for their normal homeostasis and activation during skin inflammation." (PMID 25566265, 2014).
triple-negative breast carcinoma (2 papers, 2023 to 2024). An invasive breast carcinoma which is negative for expression of estrogen receptor (ER), progesterone receptor (PR), and human epidermal growth factor receptor 2 (HER2). "A clinical trial of IL-7 and atezolizumab for the treatment of urothelial carcinoma (NCT03513952) is also ongoing, and IL-7-Fc is being used in combination with pembrolizumab in a clinical trial of triple-negative breast cancer." (PMID 38675377, 2024). "Combination of IL-7–CBD and CBD–IL-12 significantly extended the survival in the 4T1 triple-negative breast cancer model, which was completely resistant to either agent alone." (PMID 38019919, 2023).
X-linked severe combined immunodeficiency (2 papers, 2017 to 2019). "Interleukin (IL)-2, IL-4, IL-7, IL-9, IL-15, and IL-21 form a family of cytokines based on the sharing of a receptor component, the common cytokine receptor γ chain, γc, which is encoded by the gene mutated in humans with X-linked severe combined immunodeficiency (XSCID)." (PMID 29123649, 2017).
acne (1 paper, 2023). An inflammatory process of the sebaceous glands which is characterized by comedones, nodules, papules and/or pustules on the skin. "Except for IL-10, SCGF-β, and MIF-α, other cytokines (e.g., VEGF, GRO-α, Trail, MIG, IL-7, IL-17) did not exhibit any association with acne risk in the IVW primary MR analysis or other secondary analyses." (PMID 38115273, 2023).
acute cholangitis (1 paper, 2022). Cholangitis that is both sudden in onset and of a relatively short duration. "To date, suggested predictors for the severity of acute cholangitis include procalcitonin, presepsin, IL-7, and DNI." (PMID 35208579, 2022). "Several studies have investigated predictors of acute cholangitis severity, suggesting procalcitonin, presepsin, IL-7, and the delta neutrophil index (DNI) as prognostic markers." (PMID 35208579, 2022).
acute leukemia (1 paper, 2020). A clonal (malignant) hematopoietic disorder with an acute onset, affecting the bone marrow and the peripheral blood. "Whereas, IL-7 signaling is not as crucial in B-cell development in humans as it is in mice, cells from acute leukemia proliferate in response to IL-7 in vitro and have a corresponding expression of IL-7Rα." (PMID 32849527, 2020).
acute-on-chronic liver failure (1 paper, 2020). Acute-on-chronic liver failure (ACLF) is an extreme condition during the natural history of chronic HBV infection, with a relatively high short-term mortality. "In the present study, the impact of hepatic IL-7 on innate immune cells was assessed by functional experiments as well as in patients with different stages of liver cirrhosis or acute-on-chronic liver failure (ACLF)." (PMID 33584648, 2020).
adenocarcinomas of the gastric cardia (1 paper, 2019). "Similarly, systemic levels of IL-7 in adenocarcinomas of the gastric cardia were at the levels observed in controls." (PMID 31185636, 2019).